INS (insulin)
Diseases named in the same sentence as INS in open-access papers (continued):
Sharing a sentence is not in itself a finding about the gene and the disease.
diabetes (continued). "The study population was dispensed the three main diabetes drug classes available in the National Formulary for the Public Sector: Metformin (MTF), Sulphonylurea (SU) and insulin." (PMID 33961671, 2021). "Type 2 Diabetes Mellitus (T2DM) is one of the most prevalent chronic metabolic disorders, and insulin has been placed at the epicentre of its pathophysiological basis." (PMID 34502413, 2021). "As may be anticipated, high diabetes distress levels are associated with fear of insulin use in insulin-naïve patients, but it is unclear whether interventions targeting distress are as effective in insulin users as in noninsulin users." (PMID 33427667, 2021). "Type 2 diabetes mellitus (T2DM) is a heterogeneous metabolic disorder characterized by hyperglycemia and progressive decline in insulin action, followed by beta (β)-cell dysfunction to compensate for insulin resistance." (PMID 34204891, 2021). "The level of 2h-PG indicates moderate to severe insulin resistance and impaired late-phase insulin secretory response to OGTT; thus, it is different from FPG with regard to pathophysiology and odds of diabetes-related clinical outcomes." (PMID 34966358, 2021). "However, holistic studies of adipose tissue in insulin-deficient diabetes mellitus are lacking." (PMID 34888323, 2021). "A clearer picture of how diabetes affects lung volumes, flows, and gas exchange could help in creating an appropriate screening program and in choosing the most useful lung function test; on the other hand, it would also provide useful information for the implementation of inhaled insulin therapy." (PMID 33530418, 2021). "A growing body of evidence suggests a strong relationship among type 2 diabetes mellitus (T2DM), insulin, obesity, and cancer." (PMID 33477996, 2021). "As for treatment of type 2 diabetes mellitus, 12.9% of patients were treated with diet, 69.0% were treated with oral antidiabetic drugs (OAD), 11.4% were treated with OAD + insulin, and 6.7% were treated with insulin." (PMID 35010958, 2021). "The impaired effect of insulin on LPL postprandially is thought to be an important contributor to atherogenic dyslipidemia described in insulin resistance syndrome and type 2 diabetes mellitus." (PMID 34299261, 2021). "Diabetes mellitus type 2 (DM2) is characterized by hyperglycemia, insulin resistance and inadequate compensatory insulin excretion, leading to chronic structural and functional destruction of tissues and organs." (PMID 34203467, 2021). "Given the use of glucagon to rescue severe insulin-induced hypoglycaemia T1DM and its ascribed role in the hyperglycaemia of diabetes, the concept of using glucagon agonists therapeutically initially seems illogical." (PMID 34093449, 2021). "Taken together, these data suggest that the HFD induced LATS2 hyper-activation has a detrimental impact on β-cell viability, β-cell compensatory response and insulin secretion in the diet induced HFD model of β-cell decompensation and diabetes." (PMID 34389720, 2021). "DPP-4 inhibitors, which are used as diabetes drugs, block the enzymatic activity of DPP-4, therefore inhibiting degradation of the incretin hormones responsible for stimulating insulin secretion as a means of controlling blood glucose level." (PMID 34205264, 2021). "By sharing insulin release, MOR controls body weight, showing a novel target for new diabetes treatments." (PMID 34099024, 2021). "It enhanced insulin levels, reduced hyperglycemia, and prohibited changes in (GLUT4) and IRSs expression induced by diabetes." (PMID 33920079, 2021). "In insulin-treated patients with type 2 diabetes and controls without diabetes, hypoglycemia causes clinically significant and similar increases in cardiac repolarization that might increase vulnerability for serious cardiac arrhythmias and sudden cardiac death." (PMID 34085953, 2021).
diabetes (continued). "Mice receiving 1% GTE also had higher insulin immunostaining, suggesting a protective function of GTE against the damage of pancreatic β-cells during the development of diabetes." (PMID 34579032, 2021). "While less than 2% conventional RIP-hB7.1 transgenic mice developed diabetes by 8 months of age, spontaneous diabetes was commonly observed in transgenic mice that co-expressed RIP-hB7.1 and the human insulin gene β cells." (PMID 34721418, 2021). "It was reported that knockout mice for IRS 2 developed obesity and diabetes while another study showed that up-regulation of IRS mitigates obesity and diabetes by sustaining insulin signaling." (PMID 33953863, 2021). "These proteins are important insulin pathway-related factors, and the deletion of IRS1 and IRS2 genes leads to the development of diabetes in mice." (PMID 34497509, 2021). "Another study demonstrated the importance of BMAL1 in coordinating insulin secretion with the sleep–wake cycle and how BMAL1 ablation can trigger the onset of diabetes mellitus." (PMID 33807589, 2021). "DM is a chronic disease related to metabolic dysfunction initiated by insulin-compromised secretion from pancreatic β-cells, either by insulin synthesis reduction (type I diabetes) or by insulin insensitivity followed later by β-cells’ death in the Langerhans islets (type II diabetes)." (PMID 33440620, 2021). "One patient had difficult to control diabetes, requiring treatment with very high doses of U500 insulin, and was excluded from analyses of FPG and other parameters involving circulating insulin and glucose levels." (PMID 34865644, 2021). "Because of insulin resistance, progressive insufficient insulin secretion, or both, T2DM is relatively common and accounts for around 90% of all diabetes cases worldwide." (PMID 34805250, 2021). "A recent study by Sachs and colleagues showed that combined treatment with PEGylated-insulin and GLP-1-estrogen conjugate reverses STZ-induced diabetes, mainly by inducing the proliferation and redifferentiation of dedifferentiated β-cells." (PMID 33996792, 2021). "In addition, other measurements of insulin metabolism that not only aim at detecting diabetes, but any possible dysregulation of glucose metabolism such as occurring in pre-diabetes, acute hyperglycemia, impaired glucose tolerance (IGT), or stress induced hyperglycemia could be considered." (PMID 34395368, 2021). "Altogether, our data show that β-cell-specific ablation of LATS2 diminished progressive hyperglycemia and improved glucose tolerance, insulin secretion, and β-cell mass in the MLD-STZ mouse model of β-cell destruction and diabetes." (PMID 34389720, 2021). "In addition, exercise promotes a short-time increase in insulin sensitivity after the cessation of physical exertion, which, after 60 min of moderate ergometer cycling, can last up to 48 h in healthy volunteers and up to 15 h in patients with type 2 diabetes mellitus." (PMID 34682413, 2021). "In obese type 2 diabetes mellitus (T2DM) mice, it was characterized by improved glucose tolerance, decreased fasting insulin levels and sensitivity, decreased total body weight and interscapular fat mass, and increased interscapular brown fat activity." (PMID 34959419, 2021). "Nineteen people with T1D (7 females; age 35 ± 11 years; body mass index (BMI): 24.5 ± 2.7 kg/m2; HbA1c 7.3 ± 0.6% (56 ± 7 mmol/mol), diabetes duration 18 ± 11 years; 12 MDI/7 CSII; total daily insulin dose 41 ± 15 IU) were included in this analysis." (PMID 33467765, 2021). "According to research, diabetes, hypertension and other diseases can lead to higher IL6 levels in serum, while multiple reports say that genetic polymorphisms of IL6 are closely related to insulin levels and large blood vessels, and may regulate insulin secretion through pancreatic α cells." (PMID 34692849, 2021).
diabetes (continued). "It is also reported that insulin decreases the expression of ACE2 and levels of ACE2 in urine and serum are increased in patients with diabetes and positively related to blood glucose and HbA1c levels." (PMID 33801468, 2021). "Some camps also expose participants to modern diabetes management technologies, such as continuous glucose monitoring (CGM) and automated insulin delivery (AID) systems, either through investigator‐initiated studies or interactions with other campers." (PMID 34277978, 2021). "Type-1 diabetes mellitus (T1DM) is a complex metabolic disease characterized by pancreatic β-cell destruction, which results in insulin secretion deprivation and subsequently hyperglycemia." (PMID 34830046, 2021). "The results of this study showed that diabetes induction increased BW, FBG, TG, LDL-C, leptin, and TNF-α levels, and decreased insulin compared to the beginning stage." (PMID 34039404, 2021). "DM mainly consists of three types: diabetes mellitus type 2 (T2D), which accounts for approximately 90% of the total DM incidents; diabetes mellitus type 1 (T1D), which requires lifelong administration of exogenous insulin; and gestational diabetes mellitus (GDM)." (PMID 35011065, 2021). "Phosphorylated FetA was reported to play a part in insulin resistance in type 2 diabetes mellitus (T2DM) through binding the β-subunit of the insulin receptor and hindering insulin signaling." (PMID 34988120, 2021). "Type 2 Diabetes Mellitus (T2DM) is characterized by chronically elevated blood glucose (hyperglycemia) and elevated blood insulin (hyperinsulinemia)." (PMID 34447776, 2021). "90% of cases are type 2 diabetes mellitus (T2DM), a progressive condition in which the body either becomes resistant to insulin and/or gradually lose the capacity to produce enough insulin." (PMID 34126977, 2021). "C3H mice have been shown to have lower fed plasma insulin and plasma glucose levels and increased glucose tolerance compared with C57BL/6J mice and are considered a diabetes-resistant strain." (PMID 34370595, 2021). "Diabetes mellitus, particularly type 2 diabetes (T2DM), is a complex metabolic disease that is characterised by hyperglycaemia as a consequence of defects in insulin secretion, insulin action or a combination of both." (PMID 33561991, 2021). "On the contrary, a greater reduction in both insulin and HOMA-IR was reported in those participants in the highest tertile of the diabetes GRS." (PMID 34836211, 2021). "Older age, Sex (male), longer duration of diabetes, higher HbA1c, lower HDL, hypertension, taking anti-hypertensive medication, taking insulin, CVD history, presence of STDR, albuminuria and lower eGFR were significantly associated with incident stage 3 CKD." (PMID 34211028, 2021). "The Diabetes Control and Complications Trial (DCCT) definitively identified intensive insulin therapy as the gold standard of treatment to prevent the development and progression of long-term micro- and macrovascular complications." (PMID 33828529, 2021). "In gestational diabetes mellitus (GDM) or pre-existing diabetes mellitus, ACS will result in deterioration of glycemic control, severe hyperglycemia and increase in insulin requirement." (PMID 33588801, 2021). "Among 32 patients with T2D, 22 (69%) patients had diabetes complications severity index (DCSI) score ≥ 5 and 15 (47%) were dependent on insulin." (PMID 34588500, 2021). "This is why this literature review focuses on articles that study the mechanisms of this relationship, trying to analyse how BPA disrupts glucose metabolism and insulin resistance to clarify the true role of BPA in the development of obesity and diabetes." (PMID 34200822, 2021). "RS supplements reportedly improved fasting glucose and insulin, insulin sensitivity, and LDL-cholesterol concentration, especially for those with diabetes and obesity." (PMID 35010220, 2021).
diabetes (continued). "All comparisons were adjusted for age, sex, BMI, enteral nutrition, preexisting diabetes mellitus, glucocorticoid therapy, APACHE II score, SOFA score, and total insulin." (PMID 33904656, 2021). "GSK-3 protein expression and kinase activity are elevated in diabetes, while selective GSK-3 inhibitors have shown promise as modulators of glucose metabolism and insulin sensitivity." (PMID 33467194, 2021). "In obesity and diabetes, PI3K/AKT is the major insulin pathway involved in the physiological functions of various organs." (PMID 34294853, 2021). "To study the effects of insulin signaling on OSN regeneration, we experimentally induced diabetes mellitus in mice by injecting them with streptozotocin (STZ) to destroy the pancreatic islets of Langerhans and reduce insulin levels." (PMID 33906971, 2021). "Regarding auxological and nutritional status parameters, in adults with diabetes or prediabetes, NPH insulin preserved the decay of BMI-SDS." (PMID 34017312, 2021). "Mifepristone improved insulin sensitivity and adiponectin levels in mice fed a HFD, and mifepristone is reported to have anti-diabetes and anti-obesity effects in humans and mice." (PMID 34659367, 2021). "GLUT4 was expressed differently among normal humans and those with obesity and diabetes, and the overexpression of GLUT4 in skeletal muscle can alter substrate utilization and improve the benefits of insulin." (PMID 34488531, 2021). "More than 95% of all people with diabetes have type 2 diabetes mellitus (T2DM), which is characterized by obesity, insulin resistance, and insufficient insulin secretion." (PMID 34359828, 2021). "Our meta-analysis identified the following six significant and consistent factors among PE patients: higher SBP, higher DBP, higher blood insulin value, which is indicative of future diabetes development; and higher HDL, LDL, and insulin levels." (PMID 33503177, 2021). "The results showed that diabetes is well induced by MGO, as the measured blood glucose and plasma insulin levels clearly indicate this, in agreement with the study of Lee and colleagues." (PMID 34568732, 2021). "The main mechanism favouring the close relationship between diabetes mellitus and COVID-19 is the wide expression of ACE-2 receptors in endocrine pancreas, inducing insulin resistance and impaired insulin secretion." (PMID 33025384, 2021). "Biguanide metformin (MF), a first-line drug for the treatment of type 2 diabetes mellitus (T2DM), is widely used to normalize insulin sensitivity and improve glucose and lipid metabolism in patients with T2DM and metabolic syndrome." (PMID 35008624, 2021). "An in vivo study in diabetes-induced mice receiving carnosine supplements showed reduced FPG levels, decreased insulin resistance and increased β-cell mass." (PMID 34174842, 2021). "Compared with previous studies, our study has the following strengths: diabetes-related metabolic parameters, including FPG, insulin, HbA1c, HOMA-IR, as well as acute parameters such as G-iAUC and I-iAUC were all in our considerations." (PMID 35010985, 2021). "In SC therapy for type 1 diabetes mellitus (T1DM), insulin-producing cells can be generated from SCs." (PMID 34977045, 2021). "Type 2 diabetes mellitus (T2DM) is a chronic endocrine and metabolic disorder characterized by either reduced insulin production or insulin resistance resulting in drastically increased blood glucose levels." (PMID 35002950, 2021). "Nevertheless, this T2DM exploratory PCA study, together with the observation that RGS2 overexpression decreases insulin signaling in HUVEC-CS cells, supports the need for studying how RGS2 relates to diabetes in humans." (PMID 33562475, 2021). "The expression of SIRT3 in skeletal muscle cells is reduced during diabetes, and SIRT3 knockout mice exhibit increased oxidative stress, reduced oxygen consumption and impaired insulin signaling in their muscle cells." (PMID 33806509, 2021).
diabetes (continued). "The induction of diabetes with STZ consists in the acute disruption of pancreatic beta cells and the drastic interruption of insulin production." (PMID 35046830, 2021). "For example, the inhibition of Miro1 impairs mitophagy and β-cell function in T2DM, which impairs insulin signaling by inhibiting the IRS-AKT-FOXO1 pathway, leading to a reduction in glucose tolerance in diabetes." (PMID 34646830, 2021). "Type 2 diabetes mellitus (T2DM) individuals, instead, exhibits excessive blood glucose concentrations mainly due to the insufficient efficacy of circulating insulin to stimulate tissue glucose uptake (insulin resistance) and is correlated with obesity." (PMID 34570804, 2021). "Several studies have indicated that vascular actions of insulin and IGF-1 are impaired in some cardiovascular disorders, such as hypertension and diabetes." (PMID 34203897, 2021). "Plasma insulin, HOMA‐IR and 2 h OGTT also progressively increased within all three HGI subgroups with worsening diabetes status." (PMID 34558807, 2021). "Moreover, Critical unwell patients with COVID-19 and diabetes have high insulin requirements and poorer time in optimal target range for blood glucose during peak inflammatory response, which indicating the insulin treatment is necessary during the late stage of COVID-19 disease." (PMID 34367067, 2021). "Type 2 diabetes mellitus (T2DM) occurs when β-cells fail to secrete adequate insulin to keep up with demand, often influencing insulin resistance." (PMID 33440853, 2021). "Modern treatment devices, such as insulin pumps and continuous glucose monitoring (CGM) sensors, are available to and widely used by people with diabetes in most industrialized countries." (PMID 33571104, 2021). "Approximately 85-90% of diabetics have T2DM characterized by insulin resistance, meaning circulating insulin cannot bind to receptors thereby limiting downstream biochemical functions, i.e., glycolysis, glycogenesis, lipogenesis, and protein anabolism." (PMID 34037093, 2021). "This study also demonstrated a statistically significant increase in peripheral insulin sensitivity after both 3 and 30 sessions of HBOT measured using a hyperinsulinaemic clamp in those patients with type 2 diabetes mellitus." (PMID 34684171, 2021). "Type 2 diabetes mellitus (T2DM) is one of the most common endocrine and metabolic diseases and is characterized by impaired pancreatic islet β cell function and insulin resistance in insulin target tissues." (PMID 34955840, 2021). "Therefore, CaSR could couple to many G proteins within pancreatic tissue, and this may explain why no overt pancreatic phenotypes (e.g. diabetes, variations in blood glucose or insulin levels) have been reported in patients with GNA11 mutations." (PMID 34077389, 2021). "Among them, obesity and type 2 diabetes mellitus (T2DM) have attracted increasing attention, since brain insulin resistance can contribute to neurodegeneration." (PMID 34577590, 2021). "The predictive value of high FGV on the incident ESKD was more prominent in patients with young age; hypertension; dyslipidemia; a long duration of diabetes; and who were treated with ACE inhibitors or ARBs, metformin, sulfonylurea, AGI, and insulin." (PMID 34945244, 2021). "A marked increase in iNOS levels was also reported in mouse modes of diabetes, and iNOS knockout in HFD-fed mice led to improved glucose tolerance and insulin sensitivity in skeletal muscle." (PMID 33227495, 2021). "This discovery further confirms that insulin and IGF-1 are important factors for adipocyte metabolism in many disease models, including diabetes." (PMID 34563222, 2021). "Type 2 Diabetes Mellitus (T2DM) is a chronic progressive disease, defined by insulin resistance and insufficient insulin secretion to maintain normoglycemia." (PMID 34835247, 2021).